CDK1 (cyclin dependent kinase 1)
Diseases named in the same sentence as CDK1 in open-access papers (continued):
Sharing a sentence is not in itself a finding about the gene and the disease.
metabolic disease (1 paper, 2020). A congenital disorder (due to inherited enzyme abnormality) or acquired (due to failure of a metabolically important organ) disorder resulting from an abnormal metabolic process. "In this study, using our mouse model in which hepatocytes lack CDK1, the Cdk1 cKO mouse, we show that the liver, in the absence of any external stimuli, develops metabolic disease upon aging, which also affects other tissues." (PMID 33345777, 2020).
CDK1 also shares sentences with these, for which no sentence is quoted: myocardial infarction (6 papers); colorectal (5); diffuse large B-cell lymphoma (5); squamous cell carcinoma (5); digestive tumors (4); acute lymphoblastic leukemia (3); hepatitis C (3); Hodgkins lymphoma (3); mantle cell lymphoma (3); stomach cancer (3); uterine carcinosarcoma (3); acute promyelocytic leukemia (2); astrocytoma (2); Burkitt lymphoma (2); cervical adenocarcinoma (2); corticotroph adenomas (2); cystic kidney (2); fibrosarcoma (2); gastric lymphoma (2); myocarditis (2); non-Hodgkin lymphoma (2); prostate tumor (2); pulmonary arterial hypertension (2); rectal cancer (2); seminoma (2); serous ovarian cancer (2); skin cancer (2); spinal cord injury (2); thymoma (2); acute leukemia (1).
A further 77 diseases each share a sentence with CDK1 in 1 paper.